EHD1 (EH domain containing 1)
Diseases named in the same sentence as EHD1 in open-access papers (continued):
Sharing a sentence is not in itself a finding about the gene and the disease.
cancer (10 papers, 2007 to 2025). A tumor composed of atypical neoplastic, often pleomorphic cells that invade other tissues. "For instance, Liu et identified EHD1 as a significant endocytic and metastasis-associated gene which enhanced the cancer stem cells-like properties, epithelial-mesenchymal transition and metastasis of LUAD cells by antagonizing the Hippo pathway." (PMID 38495494, 2024). "Moreover, EHD1 is also involved in vesicle trafficking, which is associated with cancer migration, metastasis, and poor patient survival in NSCLC17,18." (PMID 29549343, 2018). "Conversely, EHD1 overexpression inhibited the Hippo pathway to promote cancer stemness and metastasis." (PMID 35485206, 2022). "In the 3D spheroid cancer models, fewer spheres were formed in the EHD1‐knockdown groups than in the corresponding shCtrl or untreated (UT) groups." (PMID 35485206, 2022). "f Kaplan-Meier progression-free interval curves for cancer patients with low (n = 5118) and high (n = 5117) expression of EHD1 (p < 0.0001)." (PMID 31023336, 2019). "Together, these data show that the stimulation of cancer cell angiogenesis by EHD1 is highly dependent on VEGFA." (PMID 31023336, 2019). "e Kaplan-Meier overall survival curves for cancer patients with low EHD1 expression (n = 5037) and high EHD1 expression (n = 5039; p = 0.0018)." (PMID 31023336, 2019). "Previous functional studies showed that EHD1 modulates β1 integrin function by facilitating recycling of these receptors, and promotes cancer cell migration." (PMID 27531895, 2017). "EHD1 has been found to be a significantly effective inducer during cancer progression." (PMID 35485206, 2022). "Consistent with our prior results indicating that EHD1 knockdown suppressed cancer metastasis to the lung, nude mice intravenously injected with EHD1KD+WT exhibited stronger metastatic bioluminescence signals and more metastatic nodules in the lungs compared with the corresponding controls." (PMID 35485206, 2022). "High EHD1 expression was a predictor of poor OS and progression-free interval in pan-cancer." (PMID 31023336, 2019). "Given the impact of angiogenesis in cancer metastasis, we will address whether angiogenesis is required for EHD1-induced cancer metastasis in the future." (PMID 31023336, 2019). "Moreover, using data from 10,704 tumors in the TCGA database across 26 disease sites, we evaluated the predictive value of EHD1 gene expression for the prognosis of cancer patients." (PMID 31023336, 2019). "Accordingly, we reasoned that EHD1 playing a role in the vesicle trafficking may also be related to cancer invasion and metastasis." (PMID 27531895, 2017). "What is the role of EHD1 in cancer progression is intriguing." (PMID 27531895, 2017). "Another noteworthy aspect is that EHD4 may influence chemotherapy resistance in HCC cells; other members of the EHD family, such as EHD1, have been shown to influence cellular sensitivity to chemotherapeutic drugs in certain cancers by modulating intracellular drug accumulation and efflux." (PMID 40564032, 2025). "Using the IPA commercially available software, we found that EHD1 might affect a wide range of cellular functions by regulating the expression of relevant genes, such as EMT related genes, providing a logical explaination to the higher malignancy in cancer cells with EHD1 overexpression." (PMID 27531895, 2017). "To verify the selected DEM (hsa-miR-21-5p), DEL (MIR99AHG) and 5 DEGs (RECK, TIMP3, EHD1, ERG and RASGRP1), we collected sequencing data from several cancer and normal tissues to explore the expression levels of these RNAs." (PMID 38495494, 2024). "Our findings using an EWS model have potential implications for the pro-oncogenic role of EHD1 and RTK-dependent sustenance of tumorigenesis and metastasis in other cancers." (PMID 37474760, 2023). "The upregulation of EHD1 and NAB2 clearly reveals the cancer-specific characteristic signatures of the identified genes." (PMID 17207284, 2007).
cancer (continued). "As expected, overexpression EHD1 enhanced the CSCs properties of LUAD cells, as further indicated by the 3D spheroid cancer models, the holoclone assay, stem cell marker evaluation, flow cytometric analysis of CD133‐ and CD44‐positive cells, and limiting dilution assay." (PMID 35485206, 2022). "We have provided evidence that CD133 expression is positively associated with EGFR-TKI resistance and high levels of EHD1 in patients, and NF-κB/miR-590/EHD1 acts as a novel mechanism, promoting EGFR-TKI resistance via enhanced cancer CSC-like properties in vitro and in vivo." (PMID 29549343, 2018). "Moreover, we demonstrated that miR-590 targeted the 3′-UTR of EHD1 and was regulated by NK-κB, resulting in downregulated EHD1 expression, increased erlotinib sensitivity and repressed NSCLC cancer stem-like properties in vitro and in vivo." (PMID 29549343, 2018). "EHD1, a protein of the C-terminal Eps15 homology domain-containing (EHD) family, plays a role in regulating endocytic recycling, but the mechanistic details involved in EGFR-TKI resistance and cancer stemness remain largely unclear." (PMID 29549343, 2018). "This study not only reveals the pathological role of EHD1 in NSCLC, but also suggests that it could be used as a prognostic factor and therapeutic target in NSCLC and, possibly, other cancers as well." (PMID 27531895, 2017). "However, direct evidence for regulation of RTK traffic as a proximal mechanism to activate the various distal signaling axes in EHD1-overexpressing cancers is currently lacking." (PMID 37474760, 2023). "It is, however, not clear whether EHD1 is involved in promoting EMT in cancer." (PMID 27531895, 2017).
EHD1 also shares sentences with these, for which no sentence is quoted: adenocarcinoma (2 papers); breast carcinoma (2); infection (2); lung squamous cell carcinoma (2); alopecia (1); astrocytoma (1); Bardet-Biedl syndrome type 13 (1); cardiomyopathy (1); cataract (1); cervical cancer (1); ciliopathies (1); clear renal cell carcinoma (1); dilated cardiomyopathy (1); E. coli infections of (1); genetic diseases (1); glioblastoma (1); glioma (1); Meckel syndrome, type 1 (1); microphthalmia (1); myopathy (1); neuropathy (1); otitis media (1); pancreatic endocrine neoplasms (1); Salmonella Infections (1); scoliosis (1); Sézary syndrome (1); thyroid cancer (1).